VASH2 (vasohibin 2)
Diseases named in the same sentence as VASH2 in open-access papers (continued):
Sharing a sentence is not in itself a finding about the gene and the disease.
cancer (27 papers, 2013 to 2025). A tumor composed of atypical neoplastic, often pleomorphic cells that invade other tissues. "In contrast, VASH2, expressed in infiltrating mononuclear cells or cancer cells, promotes angiogenesis and is frequently associated with poorer prognosis across various cancer types." (PMID 40483461, 2025). "However, the contradictory roles of VASH1 and VASH2 in cancers are remaining largely unknown, particularly in association with microtubule detyrosination." (PMID 39443476, 2024). "For instance, increased VASH-2 expression in cancer fibroblasts promotes cancer cell proliferation and migration through epithelial–mesenchymal (EMT) transition." (PMID 40497943, 2025). "VASH2 expression has been reported in various cancer types, where it functions to stimulate intratumoral angiogenesis in a paracrine manner." (PMID 39710372, 2024). "We found that VASH2 expression was upregulated in LUSC tissues compared to the para-carcinoma tissues, and was negatively correlated with LUSC patient prognosis." (PMID 39443476, 2024). "The expression of VASH2 has been detected in various cancer types and stimulates angiogenesis in a paracrine manner in neighboring vascular EC." (PMID 33710778, 2021). "Although the significance of VASH2 expression in cancer has become increasingly apparent, the physiological roles of VASH2 in any organs, including the kidney, remain to be elucidated." (PMID 32604722, 2020). "VASH2 expression is known to be upregulated in cancer cells and promotes cancer angiogenesis as well as growth and metastasis." (PMID 32604722, 2020). "The recent discovery of Vasohibins (VASH1 and VASH2) as TCPs revitalized the discussion about the role of tubulin detyrosination in cancer." (PMID 33114575, 2020). "VASH2 also stimulated invasion and chemotherapeutic resistance of PC cells and increased the proportion of cancer stem‐like cells in PC cells." (PMID 30318866, 2018). "In contrast to VASH1, VASH2 is detected at substantially lower levels in differentiated cells, including endothelial cells, but is abundantly expressed in cancer cells and highly undifferentiated cells such as embryonic stem cells." (PMID 29937525, 2018). "More recently, VASH2 derived from cancer cells was shown to stimulate migration of and α-SMA expression in fibroblasts." (PMID 29641565, 2018). "A recent report suggested that up-regulation of VASH2 resulted in epithelial to mesenchymal transition (EMT) of cancer cells." (PMID 29641565, 2018). "We thank Dr. Yasuhiro Suzuki of the Department of Vascular Biology, Institute of Development, Aging, and Cancer, Tohoku University, Sendai, Japan, for VASH2 antibody production and siRNA design." (PMID 29641565, 2018). "Vasohibin 2 (VASH2) has previously been identified as an agiogenenic factor and a cancer related protein." (PMID 28327155, 2017). "Vasohibin-2 (VASH2) is an angiogenic factor, and has been previously reported to be a cancer-related gene, with cytoplasmic and karyotypic forms." (PMID 24920244, 2014). "The expression of VASH2 is scarce and limited, but our earlier observations showed this expression in cancer cells and cells of the macrophage lineage." (PMID 25184477, 2014). "In this work, a tissue microarray was used to observe VASH2 and its possible role in cancer treatment." (PMID 24595063, 2014). "In addition, VASH-2 induces EMT in cancer cells by activating TGF-β1 and repressing the GATA3-ESR1 pathway under hypoxic conditions, thereby facilitating metastasis." (PMID 40497943, 2025). "However, several studies reported that VASH2 decreased chemosensitivity in cancers, which are in agreement with our findings in LUSC cells, including paclitaxel, cisplatin and gemcitabine." (PMID 39443476, 2024). "Moreover, recent reports demonstrated that VASH2 induced epithelial-to-mesenchymal transition (EMT) in cancer cells, leading to higher malignancy potential." (PMID 32604722, 2020).
cancer (continued). "However, once normal differentiated cells are transformed into cancer cells, such cell populations acquire the ability to highly express VASH2." (PMID 32604722, 2020). "The availability of VASH1/2-SVBP knockout mice will be instrumental in clarifying the apparently opposite roles of VASH1 and VASH2 in cancer and whether this is due to their secreted and/or tubulin detyrosinating activities." (PMID 33114575, 2020). "In addition, VASH2 was recently shown to promote epithelial-to-mesenchymal transition via enhanced transforming growth factor (TGF)-β signaling in cancer cells." (PMID 29641565, 2018). "Gene deletion of VASH2 or neutralizing antibody against it has been shown to inhibit cancer growth." (PMID 29641565, 2018). "We also found that VASH2 knockdown caused reduced expression of aldehyde dehydrogenase 1 (ALDH1) in PANC‐1 cells and VASH2 overexpression led to increased expression of ALDH1, another well‐known marker of cancer stem cells." (PMID 30318866, 2018). "VASH2 may be involved in cellular dedifferentiation since it induced epithelial-to-mesenchymal transition in cancer cells through accelerating TGF-β signaling." (PMID 29937525, 2018). "However, the expression level of VASH2 is extremely low in differentiated cells except for cancer cells, whereas higher expression has been observed in embryonic stem (ES) cells and induced pluripotent stem (iPS) cells." (PMID 29641565, 2018). "Based on these findings, we hypothesize that VASH2 maybe involved in the mechanisms of cancer chemotherapy." (PMID 24595063, 2014). "So, these results strongly indicate that VASH2 may be a novel target for cancer therapy and has a certain guiding role for the establishment of chemotherapy regimens." (PMID 24595063, 2014). "Based on these data, we hypothesized that VASH2 may be involved in the mechanism of cancer chemotherapy." (PMID 24595063, 2014). "VASH2 is also involved in the proliferation of hepatic and ovarian cancer." (PMID 24920244, 2014). "However, the relationship between the TCP activity of VASH2 and cancer progression or drug sensitivity currently remains unclear." (PMID 33710778, 2021). "Moreover, it currently remains unclear whether secreted VASH2 from cancer cells directly regulates tubulin detyrosination in ECs to promote their proliferation." (PMID 33710778, 2021). "Moreover, recent reports demonstrated that VASH2 could enhance TGF-β signaling in cancer cells." (PMID 29641565, 2018). "Meanwhile, no consensus has been reached regarding the chemotherapeutic use of vasohibin 2 (VASH2), which promotes the angiogenesis and proliferation of cancer cells." (PMID 24595063, 2014). "Results showed that VASH2 was highly expressed in HCC tissues and was significantly correlated with cancer differentiation." (PMID 24595063, 2014). "To test this hypothesis, we examined the role of VASH2 in the EMT and various malignant behaviors, including gemcitabine resistance, invasion, and increased cancer stem cell‐like phenotypes, of PC cells." (PMID 30318866, 2018). "In addition, we determined the gene expression of VASH2, the other important VASH family member, in different cancer cell lines." (PMID 25797264, 2015). "Therefore, it would be interesting to determine the relationship between VASH2 and the Hh pathway with regard to EMT in cancer." (PMID 25269476, 2014). "Moreover, the twin combination of VASH2 inhibition and VASH1 upregulation would be a powerful anti-cancer strategy." (PMID 23426782, 2013). "However, considering that hypoxia can promote cancer angiogenesis and EMT, enhanced VASH2 expression in cancer cells may occur in response to hypoxia." (PMID 32604722, 2020).
infection (2 papers, 2014 to 2026). The state of being infected such as from the introduction of a foreign agent such as serum, vaccine, antigenic substance or organism. "Conversely, the overexpression of VASH2 by the infection with adenovirus vector encoding human VASH2 gene significantly increased the fusion of BeWo cells." (PMID 25184477, 2014). "Western blot revealed that the expression level of VASH1 remained steady at both 16-h and 24-h post-infection, whereas VASH2 expression declined upon IAV infection, suggesting that VASH1 is the dominant detyrosination enzyme during IAV-mediated cell death." (PMID 41363857, 2026). "AdVASH2 infection significantly increased the expression of VASH2 and cell fusion of BeWo cells." (PMID 25184477, 2014). "Conversely, the overexpression of VASH2 by the AdVASH2 infection augmented the fusion of BeWo cells without any changes in the expression of Gcm-1, Syn-1, and Syn-2." (PMID 25184477, 2014).
kidney diseases (1 paper, 2020). "However, the pathophysiological roles of VASH2 in kidney diseases remain unknown." (PMID 32604722, 2020).
VASH2 also shares sentences with these, for which no sentence is quoted: acute kidney injury (1 paper); adenocarcinoma (1); CNS tumors (1); dystrophinopathies (1); esophageal squamous cell carcinoma (1); gastrointestinal tumors (1); ischemia (1); kidney injury (1); lung squamous cell carcinoma (1); pancreatic ductal adenocarcinoma (1); pediatric medulloblastoma (1); polyposis (1); type 2 diabetes (1).